SF1 (splicing factor 1)
Diseases named in the same sentence as SF1 in open-access papers (continued):
Sharing a sentence is not in itself a finding about the gene and the disease.
cancer (18 papers, 2010 to 2025). A tumor composed of atypical neoplastic, often pleomorphic cells that invade other tissues. "SF1 is recurrently mutated across cancers in a mutually exclusive fashion (i.e., indicating its analogous functionality) to RBM10, a gene found to drive aberrant splicing events in cancer." (PMID 32711844, 2020). "Whereas the correlational study of SF1 in cancers including OSCC was deficient, therefore, it is necessary to further investigate its role and regulation mechanism." (PMID 29125238, 2017). "Among the cancer-associated miRNAs, miR23a, one of the most studied miRNAs in different types of cancer, has been found to be involved, together with miR23b, in the regulation of SF-1 protein transcription." (PMID 33981288, 2021). "This could be one mechanism of generating SF1-associated cancer splice variants." (PMID 33202710, 2020). "Thus, depletion of SF1 in intestinal cells could result in changes in the expression ratios of alternatively spliced isoforms, stability of oncogenic transcripts or changes in transcriptional activity, which reduce production of cancer splice variants." (PMID 33202710, 2020). "The discovery of this regulation pattern was vital and meaningful to further explore the function and molecular mechanism of SF1 in various cancers." (PMID 29125238, 2017). "This regulatory role suggests that SF1 may influence developmental pathways and functions critical to cancer progression." (PMID 40754247, 2025). "Whether lower SF1 expression is effective in decreasing incidence in other cancer model systems with longer initiation periods remains to be examined." (PMID 33202710, 2020). "Up to now, some literatures have reported the relevance of SF1 and cancers." (PMID 29125238, 2017). "Thus, we consider that lysosomal inhibitor can be used in combination with other anti-cancer drugs such as etoposide in the treatment of steroidogenic tumors; it can either reduce the amount of Ad4BP/SF-1 or improve the cytotoxicity of anti-cancer drugs thus getting better therapeutic effects." (PMID 28325912, 2017). "Furthermore, transcription factors including SF1 (Steroidogenic Factor 1) and LRH-1 (Liver Receptor Homolog-1) have been reported to directly regulate NR0B1 expression in certain cancer types, adding further complexity to its regulation." (PMID 40864301, 2025). "Steroidogenic Factor 1 (SF-1/NR5A1), an orphan nuclear receptor, is important for sexual differentiation and the development of multiple endocrine organs, as well as cell proliferation in cancer cells." (PMID 32093223, 2020).
infection (8 papers, 2009 to 2025). The state of being infected such as from the introduction of a foreign agent such as serum, vaccine, antigenic substance or organism. "After 6 days of infection, the most efficient knockdown cells, Tat-SF1(B), showed an inability to produce reverse transcriptase above background levels." (PMID 19479034, 2009). "Indeed, the infection induced a significant reduction of steroidogenesis and Sf-1 downregulation." (PMID 40496014, 2025). "Infection with lentiviruses carrying the CXCR4 and SF1 genes was applied to construct CXCR4‐SF1‐ADSCs." (PMID 32181567, 2020). "Six inducing factors, Sry, Sox9, SF1, WT1, GATA4, and Dmrt1, were respectively transduced into mES cells by lentiviral infection according to the experimental design." (PMID 30850007, 2019). "Surprisingly, both of the Tat-SF1 knockdown cell lines showed levels of HIV-1 replication that were no different than those in the empty vector and GFP control cells after 24 hours of infection." (PMID 19479034, 2009). "HIV-1 replication was also unaffected by Tat-SF1 knockdown after 48 hours of infection (data not shown)." (PMID 19479034, 2009). "mES cells with lentiviral transduction of all the six factors, Sry, Sox9, SF1, WT1, GATA4, and Dmrt1 (mES+Trans) had a relatively less growth rate as compared to those without infection (group mES+MEF and mES+TM4)." (PMID 30850007, 2019). "SF1, SF6, and SFI8 were not expressed, or expressed at a low level, in examined strains, indicating that they do not function in the early infection stage." (PMID 29312401, 2017). "The C. militaris genome contains only one unnamed SF2 member (ATY62244) aside from homologues of Pr1C and five SF1 members in B. bassiana, suggesting that the complicated sexual/asexual cycles of C. militaris need no more SF2 proteases perhaps due to its specific infection to pupae." (PMID 32253991, 2020). "Interestingly, on forced expression of SF1, cells (irrespective of the source) had a lower proliferation rate, as assessed by the expression of proliferating cell nuclear antigen (PCNA) and direct cell counting, and became proliferation arrested three to five days after infection." (PMID 29386111, 2018).
endocrine disease (1 paper, 2011). "Therefore, the clinical spectrum of phenotypes associated with variations in SF-1 is expanding and the importance of this nuclear receptor in human endocrine disease is now firmly established." (PMID 21078366, 2011).
metabolic disorders (1 paper, 2016). "Collectively, our findings point to the important role of SF-1 in the regulation of age-dependent metabolic diseases." (PMID 27598259, 2016). "Taken together, our data underpins the importance of SF-1 in the VMH-mediated energy balance regulation and implies that SF-1 is critical for protection against age-dependent and diet induced metabolic disorders." (PMID 27598259, 2016).
neurodegenerative disease (1 paper, 2022). A disorder of the central nervous system characterized by gradual and progressive loss of neural tissue and neurologic function. "So far, no research has conclusively shown that SF1 has a role in the course of neurodegenerative diseases, including PD." (PMID 36593912, 2022).
SF1 also shares sentences with these, for which no sentence is quoted: hypospadias (5 papers); Insulin resistance (5); somatotroph adenomas (3); thyrotroph adenoma (3); Adrenal hypoplasia congenita (2); adrenoleukodystrophy (2); cholestasis (2); hyperandrogenemia (2); Hyperinsulinemia (2); Microphallus (2); myelodysplastic syndrome (2); ovarian mucinous adenocarcinoma (2); 3-beta hydroxysteroid dehydrogenase deficiency (1); adrenal pheochromocytomas (1); adrenocortical adenomas (1); angiosarcoma (1); chordoma (1); cognitive deficits (1); Congenital adrenal hypoplasia (1); Conn's syndrome (1); craniopharyngioma (1); Denys-Drash syndrome (1); depression (1); diarrhoea (1); epithelial ovarian tumors (1); Familial adenomatous polyposis (1); fibroma (1); gonadal dysgenesis (1); Headache (1); hematologic malignancies (1).
A further 29 diseases each share a sentence with SF1 in 1 paper.